CAV1 (caveolin 1)
Diseases named in the same sentence as CAV1 in open-access papers (continued):
Sharing a sentence is not in itself a finding about the gene and the disease.
lipodystrophy (continued). "It has been established by a previous study that CAV1 has a significant regulator role at FD and genetic lipodystrophies in humans." (PMID 34384444, 2021). "We directly sequenced all exons of genes associated with lipodystrophy including LMNA, ZMPSTE24, AGPAT2, BSCL2, CAV1, PTRF, and PPARγ2." (PMID 31293201, 2019). "Mutations in several genes have been found in patients with inherited lipodystrophies, including mutations in LMNA, PPARG, AKT2 and ZMPSTE24 in partial lipodystrophy, and mutations in AGPAT2, BSCL2, CAV1 and PTRF in congenital total lipodystrophy." (PMID 26987365, 2016). "Our genetic findings suggest that CAV1 might also have a role in human adipose, insulin and triglyceride metabolism, albeit only two frameshift mutations in CAV1 were found among 60 lipodystrophic patients with a normal coding sequence of known lipodystrophy genes." (PMID 18237401, 2008). "At least ten lipodystrophy-associated genes have been identified, including phosphate acetyltransferase (AGPAT2), phosphoinositide-dependent serine-threonine protein kinase (AKT2), seipin (BSCL2), caveolin 1 (CAV1) and perilipin 1 (PLIN1)." (PMID 38454882, 2024). "Lastly, CAV1 is involved in relating lipodystrophy to HCM and DCM." (PMID 36385157, 2022). "As caveolin-1 is essential for lipolysis, lipid droplet formation and lipoprotein metabolism and patients with CAV1 mutations suffer from lipodystrophy we thus show that a severe reduction of caveolae per se may lead to a similar adipose tissue phenotype." (PMID 20300641, 2010). "From genomic DNA of patients with atypical lipodystrophy and hypertriglyceridemia who had no mutations in any known lipodystrophy gene, we used DNA sequence analysis to screen the coding regions of human CAV1 (MIM 601047)." (PMID 18237401, 2008). "Since no human mutations in CAV1 have yet been reported, we screened the genomic DNA of 60 unrelated adults with partial lipodystrophy and hypertriglyceridemia and no mutation in any known lipodystrophy gene to search for coding sequence mutations in CAV1." (PMID 18237401, 2008). "The mechanisms underlying lipodystrophy and its relationship to fibrosis are not known, but may involve regulation by caveolin-1 of the ability of pluripotent cells to differentiate either into myofibroblasts or adipocytes." (PMID 24966836, 2014). "Lipodystrophies have also been noted in humans and animals lacking either cavin-1 or caveolin-1 and the association of cavin-3 with cavin-1 and caveolin-1 combined with the dependence of cavin-3 protein on cavin-1 and caveolin-1 suggests that these lipodystrophies are caused by a common mechanism." (PMID 24069528, 2013). "Marrow Adipose Tissue in lipodystrophy has not been sufficiently quantified due to the rarity of this disorder; though it has been investigated in rodents in other less severe forms of lipodystrophy (PPARγ +/- or Cav1-/-)." (PMID 35145475, 2021). "Notably, while many previously known lipodystrophy genes fell within the “lipocluster”, several did not (e.g., CAV1, PTRF, AKT2, CIDEC, LMNA)." (PMID 30940487, 2019).
glioma (34 papers, 2008 to 2025). A benign or malignant brain and spinal cord tumor that arises from glial cells (astrocytes, oligodendrocytes, ependymal cells). "To clarify the underlying role of CAV-1 in glioma, we first analyzed the associations between CAV-1 expression and clinicopathologic variables." (PMID 38298655, 2024). "To investigate the underlying role of CAV-1 in glioma, we utilized TCGA and GTEx database to acquire RNA-Seq data from 689 glioma patients and 1152 normal brain tissues." (PMID 38298655, 2024). "Subsequently, we performed Western blotting analysis to confirm the association between CAV-1 promotion of EMT in glioma cells and the PI3K/AKT signaling pathway." (PMID 38298655, 2024). "The GEPIA2 and CGGA databases demonstrated that glioma patients with higher CAV1 expression level were associated with shorter overall survival than those with a lower CAV1 expression level." (PMID 37270527, 2023). "To further evaluate the potential prognostic value of Cav-1 and VM formation in glioma, we determined the association between Cav-1 expression/VM formation and glioma patient survival time using Kaplan-Meier analysis and log-rank test." (PMID 34287575, 2021). "In cancer development and progression, FOXM1 has been implicated in regulating the expression of the human endothelial cell caveolae-marker CAV-1 and Foxm1 expression has also been linked to growth of glioma cells in tumour angiogenesis." (PMID 24391823, 2013). "Cav1 acts as a negative regulator of α5β1 integrin expression in glioma cells and specifically, loss of Cav1 confers a more aggressive phenotype." (PMID 23521716, 2013). "Notably, expression of CAV1 was significantly upregulated in high-grade glioma patients, and high expression of CAV1 is associated with a poor prognosis in glioma." (PMID 37270527, 2023). "Thus, anti-VM therapies should focus on Cav-1 or its downstream VM-associated genes to develop more effective drugs to treat glioma." (PMID 34287575, 2021). "We next sought to determine whether Cav-1 expression/VM formation is associated with clinicopathological characteristics in patients with glioma." (PMID 34287575, 2021). "In cancer research, increased Cav-1 was associated with increased vascular permeability affecting the blood-tumor barrier after exposure to various stimuli in brain microvascular endothelial cells and glioma cells." (PMID 29555979, 2018). "Therefore, while further research is needed to fully elucidate the biological functions and therapeutic potential of the caveolar network, targeting Cav-1 and caveolae-associated pathways holds promise as a novel therapeutic strategy for gliomas and other brain tumors." (PMID 40243482, 2025). "SLC47A1, GPC1, CAV1, and SLC18B1 are involved in polyamine transport; however, only CAV1 has been extensively studied in gliomas and is involved in stemness and temozolomide resistance." (PMID 40761256, 2025). "Overall, these findings indicate that Cav-1 acts as an oncogene in gliomas, promoting tumor progression and contributing to poor prognosis." (PMID 40243482, 2025). "Overexpression of CAV-1 in glioma is a strong indicator of tumor high invasiveness and is associated with poor clinical prognosis and immune infiltration." (PMID 38298655, 2024). "Our findings indicated that the knockdown of CAV-1 significantly inhibits the proliferation and metastasis of glioma." (PMID 38298655, 2024). "In glioma tissues, CAV-1 expression exhibited a correlation with unfavorable prognosis and immune infiltration among glioma patients." (PMID 38298655, 2024). "Previous studies have demonstrated that upregulation of LINC01003 plays a role in regulating cell migration through the CAV1/FAK signaling pathway in glioma." (PMID 39456519, 2024). "In conclusion, our study identifies CAV-1 as a crucial player in glioma proliferation and metastasis and immune cell infiltration." (PMID 38298655, 2024).
glioma (continued). "Our findings contribute to the comprehension of CAV-1's function and facilitate the assessment of its potential as a biomarker or therapeutic target for glioma." (PMID 38298655, 2024). "In this study, we found that knockdown of CAV-1 inhibited angiogenesis in glioma and reduced the expression of α-SMA, a vascular smooth muscle marker commonly used to evaluate angiogenesis." (PMID 38298655, 2024). "The unpaired differential expression analyses between normal and glioma groups revealed significantly higher expression of CAV-1 in tumors compared to normal tissue." (PMID 38298655, 2024). "The results showed that in glioma cell lines, the expression of CAV-1 in U87 was high, and the expression of CAV-1 in U251 cells was low." (PMID 38298655, 2024). "This study revealed that CAV-1 stimulates the in vitro proliferation, migration, and invasion of glioma cells, while also promoting the growth and angiogenesis of glioma cells in a mouse xenograft tumor model." (PMID 38298655, 2024). "In summary, these findings suggest a correlation between upregulation of CAV-1 and poor prognosis in patients with glioma." (PMID 38298655, 2024). "We also checked the methylation status of CAV1 promoters and the correlation between the methylation level of CAV1 and the glioma patient’s survival time." (PMID 37642765, 2023). "Previous studies have demonstrated that CAV1 promotes glioma cell proliferation and vasculogenic mimicry and regulates focal adhesion by effecting FAK phosphorylation." (PMID 37270527, 2023). "Our research for the first time comprehensively studied the potential functions of CAV1 and provides insights on that CAV1 is a potential novel therapeutic target in gliomas." (PMID 37642765, 2023). "Meanwhile, we checked the expression of CAV1 with the key glycolysis pathway genes HK2 and GLUT3(SLC2A3) in gliomas and found that the expression of CAV1 is positively related to HK2 and GLUT3." (PMID 37642765, 2023). "More metastasis biomarkers such as TGM2, GBP1 and IGFBP7 were checked too, and all of their expressions have a positive correlation with the expression in CAV1 in all different types of gliomas." (PMID 37642765, 2023). "In conclusion, we found that the scaffolding membrane protein CAV1 is highly expressed in glioma patients and predicts a poor prognosis, its promoters are hypomethylated and the methylation level is positively related with the glioma patients’ survival." (PMID 37642765, 2023). "Genetic addition of CAV1 alleviated the inhibitory effect of LINC01003 deficiency on the migration and p-FAK levels of glioma cells." (PMID 37270527, 2023). "Immune checkpoint targeting is a promising cancer immunotherapy and has been studied a lot in gliomas, the relationship between the expression of CAV1 and the immune checkpoints expression was explored." (PMID 37642765, 2023). "To explore the function of CAV1 in glioma, we divided the glioma patients into CAV1-high and CAV1-low groups and mined out the differentially expressed genes (DEGs)." (PMID 37642765, 2023). "The CGGA database showed that CAV1 expression was increased in glioma tissues with advanced tumor stage." (PMID 37270527, 2023). "To determine the role of the LINC01003/CAV1 axis in glioma, we employed functional rescue experiments in vitro and in vivo." (PMID 37270527, 2023). "It was used to analyze the effectiveness of CAV1 mRNA expression level AUC on distinguishing glioma tissues from normal issues." (PMID 37642765, 2023). "Our results show that CAV1 plays a critical role in glioma progression, drug resistance and glioma patients’ immunotherapy." (PMID 37642765, 2023). "The molecular role of Cav-1 in glioma cells was investigated using quantitative polymerase chain reaction (qRT-PCR) assays, western blotting, CCK-8 assays, and tubule formation assays." (PMID 34287575, 2021).
glioma (continued). "To directly assess the independent activity of Cav-1 in high grade glioma cells we modulated Cav-1 gene expression by the CRISPR system in the Cav-1 expressing U87 glioma cell line." (PMID 34490102, 2021). "Cav-1 expression was significantly upregulated in high-grade gliomas (HGG) compared with low-grade gliomas (LGG), as evidenced by dramatically increased H-scores of CAV-1 in HGG compared with those in LGG (24.85±2.922 vs 8.318±1.016, P<0.0001)." (PMID 34287575, 2021). "Taken together, these results demonstrated that Cav-1 promoted tumor cell proliferation and vascular formation in glioma, contributing to glioma development and progression." (PMID 34287575, 2021). "Both high Cav-1 protein expression and VM-forming ability were significantly correlated with shortened survival of glioma patients, suggesting that upregulation of Cav-1 or VM formation was associated with poor prognosis in glioma." (PMID 34287575, 2021). "Collectively, our study identified Cav-1 as an important regulator of glioma cell proliferation and VM formation, contributing to glioma development and progression." (PMID 34287575, 2021). "Most recently, Cav-1 has been identified as marker in glioma, promoting invasion by modulation of matrix-degrading enzyme with unfavourable outcomes in glioma patients." (PMID 34490102, 2021). "The correlations between Cav-1 and VM in glioma patients as well as between Cav-1 expression/VM formation and the clinicopathological characteristics were determined." (PMID 34287575, 2021). "In glioma, Cav-1 exhibits a tumor suppressive role both in vitro and in vivo through inhibiting TGFβ/SMAD pathway or activating apoptosis." (PMID 34287575, 2021). "Cav-1 promoted U251 glioma cell proliferation and VM formation in a Matrigel-based 3D culture model." (PMID 34287575, 2021). "On the other hand, Cav-1 was also found to be upregulated proportionally to glioma grades, which suggests a promotive role of Cav-1 in glioma progression (18, –20)." (PMID 34287575, 2021). "Our previous study has shown that Cav-1 and HIF-1α play important roles in the progress of glioma, and both of them are significantly associated with glioma prognosis." (PMID 34287575, 2021). "We found that Cav-1 was an upstream regulator governing the expression of HIF-1α in glioma cells, which suggests a promotive role of Cav-1/HIF-1α/VM axis in glioma development." (PMID 34287575, 2021). "In this study, we examined CAV-1 expression levels and VM in human glioma cell lines and in 94 human gliomas with different grades of malignancy, and present Cox proportional hazards regression." (PMID 34287575, 2021). "The effects of Cav-1 overexpression and knockdown on glioma cell proliferation and VM formation were also investigated." (PMID 34287575, 2021). "IL8 and CAV1 are reported as well-established hypoxia-responsive factor, and have been suggested to have a role in the development of aggressive gliomas." (PMID 33086616, 2020). "The main types of Ca2+ channels described in the literature and expressed by gliomas are voltage-dependent channels (Cav1 = Type L; Cav2 = Type P/Q, R, N; Cav3 = Type T) and purinergic receptors." (PMID 31531023, 2019). "A knockdown of cav-1 in C6 glioma cells nearly abolishes the 5-HT2A receptor-mediated signal transduction, and cav-1 regulates the levels of cell surface bound 5-HT7R in Hela cells (Sjögren and Svenningsson, 2007)." (PMID 28555112, 2017). "Confocal immunostaining analyses showed that about 10% of PDGFRA co-localized with caveolin-1, even though the protein is lowly expressed in glioma cells." (PMID 24489888, 2014). "Intriguingly, U0126 treatment decreased the co-localization of PDGFRA and caveolin-1 from 10% to about 2%–3% in the glioma cell line #2." (PMID 24489888, 2014). "The use of statins to inhibit cholesterol synthesis in glioma cells suppressed CAV1 expression and consequently reduced migration and survival." (PMID 21471610, 2011).
glioma (continued). "The CAV1 isoform has been identified in C6 cells, as well as in many other rat and human glioma cells." (PMID 17714745, 2008). "For ANXA5, STAT1, CD44, CAV1, and ANXA2, LGG patients with high expression possessed a worse overall survival, while low expression of MAPT was associated with poor overall survival among patients with primary gliomas." (PMID 40607003, 2025). "Overexpression of CAV-1 promoted the metastatic potential of glioma cells." (PMID 38298655, 2024). "Next, we detected the expression of CAV-1 in glioma cell lines (U87, U251, LN229, A172)." (PMID 38298655, 2024). "Studying the biological function and potential molecular mechanisms of CAV-1 in glioma could help us understand the proliferation and metastasis mechanisms of glioma." (PMID 38298655, 2024). "Our data demonstrated that knockdown of CAV-1 inhibits glioma angiogenesis." (PMID 38298655, 2024). "In conclusion, these findings suggest that CAV-1 is upregulated in glioma." (PMID 38298655, 2024). "Moreover, IHC results also demonstrated higher CAV-1 expression in glioma tissues compared to the corresponding adjacent normal tissues." (PMID 38298655, 2024). "In this study, we found that CAV-1 was upregulated in glioma." (PMID 38298655, 2024). "Notably, the silencing of CAV-1 in U87 cells significantly reduced the proliferative capacity of glioma cells, as evaluated by CCK-8 and colony formation assays." (PMID 38298655, 2024). "Moreover, according to Transwell and wound-healing assays, CAV-1 silencing decreased glioma cells invasion and migration." (PMID 38298655, 2024). "Epithelial mesenchymal transition is the most differentially enriched pathway in CAV-1 high expression phenotype, suggesting that the high expression of CAV-1 might conferred EMT process in glioma." (PMID 38298655, 2024). "More importantly, we elucidated the molecular mechanism by which CAV-1 regulates glioma metastasis." (PMID 38298655, 2024). "CAV-1 has the potential to serve as a prognostic factor and therapeutic target for glioma." (PMID 38298655, 2024). "Additionally, our analysis revealed a correlation between upregulated CAV-1 expression in glioma patients and an unfavorable prognosis." (PMID 38298655, 2024). "CAV1 expression is significantly related to immune cell infiltration in glioma." (PMID 37642765, 2023). "By comprehensive analysis of our RNA sequencing data, Whole Genome Bisulfite Sequencing (WGBS) data and public databases, we found that CAV1 is highly expressed in gliomas and its expression is positively related with pathological processes, higher CAV1 predicts shorter overall survival." (PMID 37642765, 2023). "Therefore, our study indicated that LINC01003 is a positive regulator in the CAV1/FAK signaling pathway in glioma cells." (PMID 37270527, 2023). "Despite the unknown mechanism underlying the involvement of PTRF in the development of glioma, some articles refer to PTRF/caveolin-1/caveolae in association with GBM." (PMID 37322408, 2023). "Furthermore, we showed that LINC01003 can modulate an CAV1/focal adhesion kinase (FAK) signaling pathway in glioma." (PMID 37270527, 2023). "Since GBM refers to the Grade 4 glioma, the expression of CAV1 in GBMLGG data equals the GBM data." (PMID 37642765, 2023). "In this study, we deciphered the function of CAV1 in glioma progression and drug resistance." (PMID 37642765, 2023). "This current work tests the hypothesis that Cav-1 serves as an independent prognostic marker in high grade glioma, specifically in GB." (PMID 34490102, 2021). "Our results showed the level of p-Akt was significantly elevated by Cav-1 overexpression but suppressed by siCav-1 in U251 cells, suggesting that activated Akt signal pathway may be involved in Cav-1-induced glioma cell proliferation and VM formation." (PMID 34287575, 2021).